HLA-E (major histocompatibility complex, class I, E)
Diseases named in the same sentence as HLA-E in open-access papers (continued):
Sharing a sentence is not in itself a finding about the gene and the disease.
squamous cell carcinoma (3 papers, 2015 to 2023). A carcinoma arising from squamous epithelial cells. "Because the human tumor cell lines that we analyzed weakly expressed surface HLA‐E, we transfected the squamous cell carcinoma CAL‐27 cell line, whose expression of HLA‐E was at baseline around 20%, with a plasmid encoding the HLA‐E plus the HLA‐G signal peptide to achieve HLA‐E surface expression." (PMID 37782273, 2023).
T-cell lymphoma (3 papers, 2019 to 2024). "It has been found that murine TAP-/- T-cell lymphoma cells present immunogenic alternative peptides on the mouse HLA-E ortholog, Qa1, and CD8+ T-cell clone production was restricted." (PMID 39301027, 2024).
Bladder Cancer (2 papers, 2025). "Another study reported a similar correlation between HLA-E expression and disease-free survival in bladder cancer patients." (PMID 40066089, 2025).
bladder tumors (2 papers, 2023 to 2024). "NKG2A+ CD8+ T cells inhibited by tumors through HLA-E can partly restore upon NKG2A blockade in an HLA-E-dependent manner in the bladder tumors." (PMID 39229258, 2024).
brain cancer (2 papers, 2009 to 2021). A primary or metastatic malignant neoplasm affecting the brain. "In brain cancer, low expression of classical HLA class I genes (HLA-A, -B, and –C) coupled with up-regulation of nonclassical genes (e.g., HLA-E and HLA-G) likely contributes to immune escape by tumor cells with various somatic mutations." (PMID 19774073, 2009).
chronic lung allograft dysfunction (2 papers, 2016 to 2022). Chronic lung allograft dysfunction encompasses a range of pathologies that cause a transplanted lung to not achieve or maintain normal function. "HLA-E upregulation in rejecting allografts and presentation of distinct variants of virally encoded UL40 peptides may thereby contribute to NK cell-triggered graft injury, as has been shown for lung transplant recipients who developed chronic lung allograft dysfunction." (PMID 35401541, 2022).
clear renal cell carcinoma (2 papers, 2021 to 2024). "In addition, VSIG4 and HLA-E were found to be co-expressed in M2 macrophages in renal clear cell carcinoma, enriched in neutrophil activation, and involved in immune responses." (PMID 39726813, 2024).
dengue (2 papers, 2019 to 2020). "To address this question, we analyzed peripheral blood mononuclear cell (PBMC) samples from a Panamanian cohort of adult dengue patients and healthy controls for expression of total HLA class I and HLA-E." (PMID 31396492, 2019).
endometrial cancer (2 papers, 2023 to 2025). Primary or metastatic malignant neoplasm involving the endometrium (mucous membrane that lines the endometrial cavity). "Low HLA-E expression is associated with better overall survival in endometrial cancer." (PMID 37178414, 2023).
graft versus host disease (2 papers, 2016 to 2025). An immune system disorder that occurs after allogeneic hematopoietic stem cell transplant and is a reaction of donor immune cells against host tissues. "The presence of this genetic variant—HLA-E*01:03 allele—shows a rather protective effect, as was observed also in an allogeneic transplant setting in the context of acute graft-versus-host disease or in HIV infection." (PMID 41153412, 2025).
head and neck squamous cell carcinoma (2 papers, 2022 to 2024). A squamous cell carcinoma that arises from any of the following anatomic sites: lip and oral cavity, nasal cavity, paranasal sinuses, pharynx, larynx, and salivary glands. "Additionally, monalizumab significantly enhances NK cytotoxicity in head and neck squamous cell carcinoma (HNSCC) cell lines with high expression of HLA-E." (PMID 39221244, 2024).
juvenile idiopathic arthritis (2 papers, 2014 to 2023). Juvenile idiopathic arthritis (JIA) is the term used to describe a group of inflammatory articular disorders of unknown cause that begin before the age of 16 and last over 6 weeks. "In support of this hypothesis, we have previously demonstrated that HLA-E is upregulated in peripheral blood and synovial monocytes from patients affected by juvenile idiopathic arthritis, thus suggesting that HLA-E upregulation takes place during autoimmune and inflammatory conditions." (PMID 24741633, 2014).
monoclonal gammopathy of undetermined significance (2 papers, 2024 to 2025). "To study the role of HLA-E in MM, we first analyzed mRNA gene-expression data from healthy donors, individuals with monoclonal gammopathy of undetermined significance (MGUS), smoldering MM (SMM), and MM in publicly available datasets, such as GSE4452 and GSE5900." (PMID 38902472, 2024).
nasopharyngeal carcinoma (2 papers, 2014 to 2015). A carcinoma arising from the nasopharyngeal epithelium. "Indeed, the surface levels of HLA-E have been shown to affect inhibitory activity in vitro, and HLA-E polymorphisms have been associated with nasopharyngeal carcinoma, and recurrent spontaneous abortions." (PMID 25566263, 2014). "The influence of the HLA-E locus on the genetic background of EBV-induced tumors has also been studied in nasopharyngeal carcinoma (NPC), an EBV-associated malignancy with a restricted racial and geographical distribution." (PMID 26261988, 2015).
Nephropathy (2 papers, 2019 to 2021). A nonspecific term referring to disease or damage of the kidneys. "To elucidate whether HLA-E polymorphisms influence BKPyV replication and nephropathy, we determined the HLA-E genotype of 278 living donor and recipient pairs." (PMID 31394776, 2019). "In another study, living-donor kidney recipients with HLA-E*01:01/01:01 experienced less BK polyoma virus (BKPyV) reactivation than recipients with other genotypes, and BKPyV-induced nephropathy occurred more frequently in recipients carrying the HLA-E*01:03 allele." (PMID 34295330, 2021). "Considering the time course of the occurrence of nephropathy, recipients with PyVAN were more likely to carry the HLA-E*01:03 allelic variant than those without PyVAN (Kaplan–Meier analysis p = 0.03; OR = 4.25; CI (95%) 1.11–16.23)." (PMID 31394776, 2019).
oral cancer (2 papers, 2023). "Based on these data and considering the high expression of HLA-E and PD-L1 on the surface of oral cancer cells, we selected these two molecules as potential OSCC biomarkers." (PMID 37483588, 2023).
oral squamous cell carcinomas (2 papers, 2023 to 2024). "The aim of this study is to investigate the sex differences in HLA-E expression and its solute component in relation to clinicopathological parameters and survival rates in patients with oral squamous cell carcinoma (OSCC)." (PMID 38069020, 2023). "Therefore, immunohistochemical HLA-E expression was retrospectively analysed in a cohort of oral squamous cell carcinomas (OSCC) after surgical therapy." (PMID 38069020, 2023). "The expression of molecules such as HLA-E and PD-L1 is independent of the oral lesion’s histopathological grade; levels of these molecules are comparable in OPMDs and oral squamous cell carcinomas, with FM 1.6 in our case." (PMID 39676869, 2024).
psoriasis (2 papers, 2019 to 2025). An autoimmune condition characterized by red, well-delineated plaques with silvery scales that are usually on the extensor surfaces and scalp. "Meanwhile, LTA, TDRKH, and DDR1 were expressed exclusively in T cells from psoriasis biopsy samples, while HLA-E and ICAM3 exhibited psoriasis-specific- expression." (PMID 40564099, 2025).
relapsing remitting MS (2 papers, 2012 to 2022). "Expression of HLA-E was generally low, but significantly increased on CD4+ cells from primary progressive MS patients when compared with healthy controls (p<0.005) and relapsing remitting MS patients (p<0.031)." (PMID 23049954, 2012). "HLA-E protein abundance is higher in relapsing remitting MS patients compared to patients with other non-MS inflammatory disorders." (PMID 35592112, 2022).
abortion (1 paper, 2021). the ending of pregnancy by removing a fetus or embryo before it can survive outside the uterus. "The level of HLA-E in T-EVs from unexplained recurrent spontaneous abortion (URSA) patients was lower than that in normal pregnancy (NP) and RSA patients who had an abnormal embryo karyotype (AK-RSA)." (PMID 34803505, 2021).
acute hepatitis B virus infection (1 paper, 2017). A new infection by the hepatitis B virus, which can be transmitted by direct contact of infected blood with mucous membranes or open areas of the skin. "Patients with acute hepatitis B virus infection were found to have increased numbers of NKG2A+ NK cells in their peripheral blood and blocking CD94/NKG2A interaction with HLA-E was found to promote clearance of hepatitis B virus very efficiently in mice." (PMID 28008151, 2017).
acute lymphoid leukemia (1 paper, 2019). "Therefore, the identification of physiopathological HLA-E peptide ligands and development of single high affinity receptors such that have been shown for chimeric antigen receptors on T cells against acute lymphoid leukemia is one obstacle that needs to be overcome for future therapy concepts." (PMID 30909402, 2019).
adenoma (1 paper, 2024). A neoplasm arising from the epithelium. "In the LNM-positive group compared to the control adenoma, there were significant increases in gene expression for CCL15, SSX1, and KRT5 genes, alongside significant decreases in HLA-E, ITPK1, ANXA1, and TXNIP genes across the head, proximal stalk, and distal stalk regions." (PMID 38256174, 2024).
amyotrophic lateral sclerosis (1 paper, 2025). Amyotrophic lateral sclerosis (ALS) is a neurodegenerative disease characterized by progressive muscular paralysis reflecting degeneration of motor neurons in the primary motor cortex, corticospinal tracts, brainstem and spinal cord. "A recent study reported a reduction of HLA-E expression in endothelial cells of the BBB in amyotrophic lateral sclerosis as well as in patients with frontotemporal lobar degeneration, suggesting that downregulation of HLA-E may facilitate BBB breakdown." (PMID 41283666, 2025).
anaplastic astrocytoma (1 paper, 2020). "We found that HLA-E expression was significantly higher in diffuse astrocytomas than it in oligodendrogliomas (− 0.255 ± 0.762 versus − 0.636 ± 0.879, p = 0.032, t-test), while no such difference was observed between anaplastic astrocytomas and anaplastic oligodendrogliomas (p = 0.671, t-test)." (PMID 32066399, 2020).
astrocytic tumor (1 paper, 2020). A glial tumor of the brain or spinal cord showing astrocytic differentiation. "To further identify the clinical significance of HLA-E expression in diffuse glioma, we also compared HLA-E mRNA expression between astrocytic tumors and oligodendroglial tumors in LGGs and AGs." (PMID 32066399, 2020).
BK-virus nephropathy (1 paper, 2019). "In such cases of combined BK virus nephropathy and CMV replication, it became evident that both events were associated with HLA-E*01:03 recipient carrier status." (PMID 31394776, 2019).
brucellosis (1 paper, 2024). Brucellosis is a bacterial infection that spreads from animals to people via unpasteurized dairy products or by exposure to contaminated animal products or infected animals. "Interestingly, a series of commonly upregulated genes were identified in brucellosis patients, with seven genes/transcription factors (RGS1, DUSP1, FOS, PPP1R15A, TNFAIP3, HLA‐E, and ZFP36) being the most frequent (nine times among nine clusters)." (PMID 39135683, 2024). "Similarly, an elevated expression of HLA‐I molecules was observed in brucellosis patients relative to other conditions, including canonical HLA‐I genes HLA‐A/B, and noncanonical HLA‐I gene HLA‐E/F." (PMID 39135683, 2024).
celiac disease (1 paper, 2022). An autoimmune genetic disorder with an unknown pattern of inheritance that primarily affects the digestive tract. "The most significantly up-regulated genes in celiac disease were TAP1, HLA-E, HCP5, STAT1, GBP1, STAT1, LOC100419583, and GBP4 and the down-regulated ones were IDS, PKIB, FBXO2, OXT, and ADI1." (PMID 36011206, 2022).
cervical tumour (1 paper, 2012). "However, the function of high HLA-E expression on cervical tumour cells and on the tumour cells of cervical AC in particular remains uncertain." (PMID 22947189, 2012). "Here, we also suggest that the inhibiting and activating functions of HLA-E may be related to the delicate balance between immune escape and immune surveillance in cervical tumours." (PMID 22947189, 2012).
chronic hepatitis (1 paper, 2022). An active inflammatory process affecting the liver for more than six months. "NKG2A recognizes the non-classical MHC-I molecule HLA-E, and the expression of NKG2A is found to be up-regulated in peripheral blood NK cells of patients with chronic hepatitis." (PMID 35413989, 2022).
chronic hepatitis C infection (1 paper, 2018). "In our study, we analyzed the expression of HLA-E in the liver and its association with the severity of liver disease in chronic hepatitis C patients." (PMID 29951556, 2018). "Thus, an impaired function of NK cells can predispose the evolution to chronic hepatitis C infection and to the progression of liver fibrosis, the HLA-E molecule being a key component of this process via its interaction with inhibitory NK cell receptors." (PMID 29951556, 2018). "It indicates that HLA-E expression may have an immunomodulatory effect and a possible role in the severity of liver disease in chronic hepatitis C." (PMID 29951556, 2018). "The nonclassical HLA-E molecule might have an immunomodulatory effect and a possible role in the severity of liver disease in chronic hepatitis C. Knowledge of the expression profile of HLA-E may aid in the identification of HCV-infected patients with a worse prognosis and less favourable outcomes." (PMID 29951556, 2018).
Crohn disease (1 paper, 2021). A gastrointestinal disorder characterized by chronic inflammation involving all layers of the intestinal wall, noncaseating granulomas affecting the intestinal wall and regional lymph nodes, and transmural fibrosis. "We first compared differential gene expression of two class Ib MHC molecules (HLA-E and CD1d) and one class Ia MHC molecule (HLA-A) between non-inflamed and inflamed colon from descending and ascending colon in refractory Crohn’s disease (CD) using the CERTIFI cohort (GSE100833)." (PMID 34911745, 2021).
cutaneous melanoma (1 paper, 2021). A primary melanoma arising from atypical melanocytes in the skin. "NKG2A is, contrary to primary NK cells, one of the few inhibitory receptors expressed by CD276-CAR NK-92 cells and their respective tumor cell ligands, HLA-E and HLA-G, are commonly overexpressed in cutaneous melanoma." (PMID 33925968, 2021).
diffuse astrocytoma (1 paper, 2020). A low-grade (WHO grade II) astrocytic neoplasm. "For patients with diffuse astrocytomas, lower HLA-E expression still seemed to correlate with better clinical outcomes, but the results were not statistically significant (p = 0.128 for PFS and p = 0.080 for OS, Log-rank test)." (PMID 32066399, 2020). "Compared with oligodendrogliomas, diffuse astrocytomas showed higher expression of HLA-E." (PMID 32066399, 2020). "Moreover, HLA-E expression was significantly higher in diffuse astrocytomas than oligodendrogliomas (p = 0.032, t-test)." (PMID 32066399, 2020). "In order to further investigate the predictive value of HLA-E expression in LGG patients, we performed Kaplan-Meier analysis in patients with diffuse astrocytomas and oligodendrogliomas respectively." (PMID 32066399, 2020).
dyslipidemia (1 paper, 2024). "Similarly, no direct evidence was found to explain the role of HLA‐E in dyslipidemia, which encodes nonclassical histocompatibility leukocyte antigens Ib (HLA‐Ib) molecules involved in self‐surveillance and adaptive immune reaction." (PMID 39673281, 2024).
encephalitis (1 paper, 2021). An acute inflammatory process affecting the brain parenchyma. "The Japanese encephalitis virus, a flavivirus responsible for encephalitis in Asian children, upregulates HLA-E cell-surface levels, coupled to an enhanced release of sHLA-E, suggesting a potential immuno-evasive strategy likely developed by the viral agent against host mediated immune responses." (PMID 34642395, 2021).
esophageal adenocarcinoma (1 paper, 2024). A malignant tumor with glandular differentiation arising predominantly from Barrett mucosa in the lower third of the esophagus. "Additionally, while this study focused on ESCC confirmed by histopathology, the prognostic significance of NK cell status and HLA-E expression in esophageal adenocarcinoma remains unclear." (PMID 39845968, 2024).
gastric tumor (1 paper, 2010). "Although both autologous gastric tumor cell lines did not express HLA-E, we can not rule out that autologous tumor cell recognition will not be affected in HLA-E expressing tumors." (PMID 20937115, 2010).
hantavirus infection (1 paper, 2020). "Expansion of adaptive NK cells in CMV-seropositive patients was previously reported in acute hantavirus infection and was associated with the up-regulation of both class I MHC and HLA-E on the virus-infected cells." (PMID 32826343, 2020).
Hepatitis (1 paper, 2025). Inflammation of the liver. "NK cells’ increased expression of NKG2A during long-term hepatitis C virus (HCV) infections is linked to a compromised immune response, as HLA-E and NKG2A interactions inhibit the activity and viral clearance of NK cells." (PMID 40497938, 2025).
hepatitis B (1 paper, 2016). "Six of 16 designated HLA-E, HLA-G, and HLA-F haplotypes were shown to be associated with risk for hepatitis B or HCC." (PMID 27243039, 2016). "Four SNPs (rs17875380, rs41557518, rs114465251, and rs115492845), in nonclassical class I alleles, were shown to be associated with altered susceptibility to HBV or HCC, while HLA-F ∗01:04, HLA-G ∗01:05N, and HLA-E ∗01:01 are associated with hepatitis B or hepatitis B complicated with HCC." (PMID 27243039, 2016).
Hodgkins lymphoma (1 paper, 2020). A heterogeneous group of malignant lymphoid neoplasms of B-cell origin characterized histologically by the presence of Hodgkin and Reed-Sternberg (HRS) cells in the vast majority of cases. "Interestingly, the HLA-E*01:01 allele seems to be underrepresented in classical Hodgkin lymphomas, especially among Epstein Barr virus (EBV)-positive cases compared to healthy controls." (PMID 33218185, 2020).
IgA nephropathy (1 paper, 2024). "We found that Apo A-IV, HLA-E, and AIF1 were negatively associated with IgA nephropathy; however, HLA-E and AIF1 were positively associated with other CKD types." (PMID 38898508, 2024).
inflammatory bowel disease (1 paper, 2021). A spectrum of small and large bowel inflammatory diseases of unknown etiology. "Finally, in patients with inflammatory bowel disease, we found upregulation of HLA-E, a Qa-1b analog with inflammation and biologic non-response, in silico, suggesting the importance of this regulatory mechanism across species." (PMID 34911745, 2021).
intracranial meningioma (1 paper, 2020). A meningioma that arises within the cranial cavity.
kidney stone (1 paper, 2025). "Five of these protein ratio pairs positively promote kidney stone development: BAIAP2/MME protein level ratio, GRPEL1/MME protein level ratio, HLAE/IL15 protein level ratio, CEACAM1/GGT1 protein level ratio and BTN2A1/IL18BP protein level ratio." (PMID 40673688, 2025).